NDE1 (nudE neurodevelopment protein 1)
Description:
Required for centrosome duplication and formation and function of the mitotic spindle. Essential for the development of the cerebral cortex. May regulate the production of neurons by controlling the orientation of the mitotic spindle during division of cortical neuronal progenitors of the proliferative ventricular zone of the brain. Orientation of the division plane perpendicular to the layers of the cortex gives rise to two proliferative neuronal progenitors whereas parallel orientation of the division plane yields one proliferative neuronal progenitor and a postmitotic neuron. A premature shift towards a neuronal fate within the progenitor population may result in an overall reduction in the final number of neurons and an increase in the number of neurons in the deeper layers of the cortex. Acts as a RAB9A/B effector that tethers RAB9-associated late endosomes to the dynein motor for their retrograde transport to the trans-Golgi network.
Synonyms: NudE; FLJ20101; NDE; HOM-TES-87; LIS4; MHAC; NUDE1
Tractability: Small molecule: a structure with a bound ligand is known. PROTAC: ubiquitination databases record sites on it; its protein half-life has been measured.
Gene: Protein-coding gene on chromosome 16 (15,643,267 to 15,734,691, forward strand). Ensembl gene ENSG00000072864.
Subcellular location: Cytoplasm, cytoskeleton; Cytoplasm, cytoskeleton, microtubule organizing center, centrosome; Chromosome, centromere, kinetochore; Cytoplasm, cytoskeleton, spindle; Cleavage furrow; Cytoplasmic vesicle membrane
Pathways (Reactome):
Cell Cycle: AURKA Activation by TPX2; Amplification of signal from unattached kinetochores via a MAD2 inhibitory signal; EML4 and NUDC in mitotic spindle formation; Loss of Nlp from mitotic centrosomes; Loss of proteins required for interphase microtubule organization from the centrosome; Mitotic Prometaphase; Recruitment of NuMA to mitotic centrosomes; Recruitment of mitotic centrosome proteins and complexes; Regulation of PLK1 Activity at G2/M Transition; Resolution of Sister Chromatid Cohesion; Separation of Sister Chromatids
Organelle biogenesis and maintenance: Anchoring of the basal body to the plasma membrane
Signal Transduction: RHO GTPases Activate Formins
Gene Ontology:
Molecular function: identical protein binding; protein binding; microtubule binding; protein domain specific binding
Biological process: cerebral cortex development; chromosome localization; establishment of mitotic spindle orientation; cell migration; centrosome duplication; centrosome localization; chromosome segregation; microtubule nucleation; mitotic centrosome separation; vesicle transport along microtubule; microtubule organizing center organization; neuron migration
Cellular component: centrosome; cytoplasmic vesicle membrane; kinetochore; membrane; cytosol; kinesin complex; spindle pole centrosome; cleavage furrow; cytoskeleton; microtubule organizing center; spindle; synapse
Genetic constraint (gnomAD): Loss-of-function variants: 28 observed, 45.09 expected, observed/expected ratio (o/e) 0.62, 90% interval 0.46 to 0.85. The upper end of that interval is the gene's LOEUF score, 0.85, which puts it in group 3 of 6, group 1 being the genes least tolerant of losing a copy. Missense variants: 441 observed, 456.12 expected, observed/expected ratio (o/e) 0.97, 90% interval 0.89 to 1.05. Synonymous variants: 184 observed, 181.76 expected, observed/expected ratio (o/e) 1.01, 90% interval 0.9 to 1.14.
Gene-disease validity (ClinGen):
ClinGen rates the evidence that NDE1 causes each of these diseases.
microcephaly with lissencephaly and/or hydranencephaly (autosomal recessive): Definitive. A brain disorder caused by biallelic variants in NDE1 that is characterized by extreme microcephaly (typically head circumference of more than 10 standard deviations (SD) below the mean), profound motor and intellectual disability, spasticity, and incomplete cerebral formation.
Homologues: Orthologues: macaque NDE1 (95% identical), chimpanzee NDE1 (95% identical), pig NDE1 (92% identical), rabbit NDE1 (91% identical), guinea pig NDE1 (89% identical), mouse Nde1 (86% identical), rat Nde1 (83% identical), tropical clawed frog nde1 (69% identical), zebrafish nde1 (58% identical), Drosophila melanogaster nudE (33% identical), Caenorhabditis elegans nud-2 (23% identical). Paralogues in human: NDEL1 (56% identical).
Diseases named in the same sentence as NDE1 in open-access papers:
NDE1 is named in the same sentence as 43 diseases in open-access papers, as found by Europe PMC text mining. Sharing a sentence is not in itself a finding about the gene and the disease. The quoted sentences say what the papers report.
microcephaly (31 papers, 2009 to 2025). A congenital or acquired developmental disorder in which the circumference of the head is smaller than normal for the person's age and sex. "Variants of NDE1 have been associated with neurodevelopmental disorders, particularly microcephaly related diseases of cortical development." (PMID 41296379, 2025). "AR micro-lissencephaly caused by a mutation in NDE1 (Lissencephaly 4 with microcephaly (OMIM #609449)), a regulator of cell cycle progression, leads to the FBDS by interfering with neuronal proliferation and migration." (PMID 40143324, 2025). "Heterozygous deletions or mutations of LIS1 (also known as PAFAH1B1) result in lissencephaly (smooth brain); biallelic mutations or deletions in NDE1 have been shown to result in microcephaly (small brain), microlissencephaly or microhydranencephaly." (PMID 38194050, 2024). "While the loss of function in NDE1 leads to microcephaly-related malformations of cortical development (MCDs), NDEL1 variants have not been detected in MCD patients." (PMID 38194050, 2024). "Nde1 mutation is largely associated with microcephaly, while Lis1 mutation is associated with lissencephaly, suggesting that Lis1 and Nde1/Ndel1 have unique functions during development." (PMID 35493069, 2022). "Here, we discuss the role of NDE1 in cell cycle regulation of neural progenitor cells, specifically its role in INM and how mutations in NDE1 result in various human diseases in various human diseases that are often characterized by microcephaly." (PMID 33390896, 2020). "We also conducted literaturte review to compare the clinical phenotypes of our patient to those of cases previously reported with NDE1 mutations, and found all patients had mental retardation, severe microcephaly, and corpus callosum agenesis." (PMID 29191162, 2017). "Depletion of NDE1 in embryonic rat brains causes cell cycle arrest of neural progenitor cells and severe microcephaly consistent with a role of NDE1 in maintaining replicating progenitor cells." (PMID 28361305, 2017). "Congenital severe microcephaly is very rare, and NDE1 deletion and genetic mutations are important contributors." (PMID 29191162, 2017). "To date, several cases of autosomal recessive extreme microcephaly caused by NDE1 mutations have been reported." (PMID 29191162, 2017). "The current study, however, reveals three alternative mechanisms associated with a severe microcephaly-causing gene, NDE1, and is the first to link aberrations in apical INM to human disorders of corticogenesis." (PMID 27553190, 2016). "Human mutations in the NDE1 gene have been associated with cortical malformations and severe microcephaly." (PMID 27553190, 2016). "Recent studies have revealed severe cases of microcephaly resulting from human mutations in the NDE1 gene, which is involved in the regulation of cytoplasmic dynein." (PMID 27553190, 2016). "Similar to our Tcof1/Treacle loss-of-function studies, mitotically-arrested cells are considerably increased in association with altered spindle orientation in the VZ of Nde1 mutant mice which exhibit defects in cortical neurogenesis and microcephaly." (PMID 22479190, 2012). "NDE1 (nudE neurodevelopment protein 1), whose mutations in human patients can lead to a severe microcephaly with lissencephaly, is involved in centrosome duplication and mitotic spindle assembly, attachment of microtubules to kinetochores and proper neuronal migration." (PMID 35069108, 2021). "Our data support the idea that microcephaly in humans caused by inactivating mutations in NDE1 might be due to abnormally long cilia and/or reduced Hedgehog activity (GLI2)." (PMID 34518642, 2021). "Patients who have mutations in NDE1 exhibit congenital microcephaly as a primary phenotype." (PMID 33390896, 2020).
microcephaly (continued). "The importance of the NDE1 protein for neurodevelopment more generally has been dramatically demonstrated in individuals with biallelic loss of the functional NDE1 gene, leading to severe microcephaly phenotypes, sometimes described in conjunction with lissencephaly or hydrocephaly." (PMID 29142105, 2017). "This is the first Chinese reported with microcephaly caused by NDE1 mutations." (PMID 29191162, 2017). "However, human NDE1-associated microcephaly is much more severe than the forms of the disorder involving mitotic spindle assembly genes, such as ASPM and WDR62 (refs 4, 5)." (PMID 27553190, 2016). "Our data suggest that homozygous loss of NDE1 function may be a more common cause of autosomal recessive severe microcephaly, and may be present in outbred families." (PMID 23704059, 2013). "Our observations suggest that mutations (including deletion) of NDE1 may prove to be a relatively common cause of severe congenital microcephaly." (PMID 23704059, 2013). "Nde1 is a candidate gene for lissencephaly-4, which is characterized by both microcephaly and lissencephaly." (PMID 34502215, 2021). "In mice, depleting Nde1 results in microcephaly, albeit to a relatively lesser degree than in humans." (PMID 33390896, 2020). "As the documented cases of NDE1 mediated microcephaly increase, so does the need to understand the basic biology of these pathogenic variants." (PMID 33390896, 2020). "Single nucleotide polymorphism (SNP) chromosomal microarray analysis (CMA) and muation screening of NDE1 gene were performed in an 8-month patient with severe congenital microcephaly, and/or his parents." (PMID 29191162, 2017). "By preventing nuclear migration to the ventricular surface of the developing brain, we predicted that NDE1 knockdown, but not NDEL1 knockdown, would prevent RGP cells from dividing, identifying a potential NDE1-specific microcephaly mechanism." (PMID 27553190, 2016). "The current study was initiated to determine which NDE1 roles contribute most significantly to the extreme form of microcephaly seen in human patients." (PMID 27553190, 2016). "We then undertook copy number studies of 16p13.11 and sequencing of NDE1 in nine additional patients with a similar severe microcephaly, agenesis of the corpus callosum, and FBD-like phenotype." (PMID 23704059, 2013). "Because microcephaly was observed in two of the three adult patients with typical deletions and in one of the two fetuses with deletion, NDE1 was considered an excellent candidate gene for this phenotype." (PMID 18550696, 2009). "Moreover, NDE1 has been postulated to be responsible for microcephaly that is often seen in those with a 16p13.11 microdeletion." (PMID 39221225, 2024). "Knockout of Nde1 in mice leads to abnormalities in the cerebral cortex and microcephaly." (PMID 39473442, 2024). "Unlike patients with NDE1 mutations, our patients did not exhibit microcephaly, suggesting that the p.R105P variant does not have a major impact on neurogenesis." (PMID 38194050, 2024). "It is interesting to note that mutations in human NDE1 are causative of microcephaly, not lissencephaly, revealing that these proteins likely have distinct roles during brain development." (PMID 32692650, 2020). "Although experimental findings in mouse models and cell culture have provided insight into the functional mechanism of Nde1, these studies do not recapitulate the pathophysiology of NDE1 mutation-linked microcephaly in humans." (PMID 33390896, 2020). "Although Nde1–/– mice also exhibit decreased cortical size, the microcephaly observed in patients is much more severe, which suggests NDE1 may play a more crucial role in the cortical development of humans than it does in mice." (PMID 33390896, 2020).
microcephaly (continued). "We observed one single m6A site near the stop codon in 7 microcephaly-related E-SMRs, including Brca2, Cep152, Ddx11, Nde1, Kif14, Stil and Cdk5rap2, 3 polymicrogyria-related E-SMRs (Eomes/Tbr2, Pax6 and Foxp2), and 3 megalencephaly-related E-SMRs (Gli3, Ccnd2 and Kif7)." (PMID 32992647, 2020). "NDE1 is a critical pathogenetic gene in severe congenital microcephaly." (PMID 29191162, 2017). "Herein we report that a patient, with severe congenital microcephaly, had 16p13.11 deletion containing NDE1 gene combined with a novel NDE1 mutation on the non-deleted homolog." (PMID 29191162, 2017). "Given that microcephaly and brain malformations are the major recurrent characteristic in our patients with deletions, NDE1 was believed to be a good candidate for a dosage-sensitive gene that might underlie the features of these deletions." (PMID 18550696, 2009). "Therefore, differences in the progenitor pool requirements for cortical development may account for the varying severity of NDE1-mediated microcephaly reported between humans and mice." (PMID 33390896, 2020). "A number of microcephaly genes have been identified, including ASPM, microcephalin/BRIT1, CDK5RAP2/Cep215, CENPJ/CPAP, SIL/STIL, WDR62, and NDE1 (refs 3, 4, 5)." (PMID 27553190, 2016). "Whereas LIS1 mutations generally manifest as classical lissencephaly (lissencephaly-1), characterized by disorganized lamination of the cortex without microcephaly, NDE1 encephalopathy presents itself as extreme brain atrophy that includes microcephaly and lissencephaly (lissencephaly-4)." (PMID 33390896, 2020). "Sequencing NDE1 and CMA in patients with severe congenital microcephaly may be warranted." (PMID 29191162, 2017). "In addition, there were no variants in the NDE1 locus, which is adjacent to the MKL2 locus (16p13.11 and 16p13.12, respectively) and has been associated with severe microcephaly with lissencephaly 27–29." (PMID 23692340, 2014).
schizophrenia (22 papers, 2009 to 2025). A major psychotic disorder characterized by abnormalities in the perception or expression of reality. "One of the most repressed genes is NDE1, which is essential for progenitor cell proliferation and neuronal migration and whose mutations are associated with schizophrenia." (PMID 40725218, 2025). "NDE1 encodes for nude neurodevelopment protein 1, which is essential for mitosis and neurodevelopment in patients with schizophrenia and other major psychiatric disorders." (PMID 37013606, 2023). "Schizophrenia is associated with duplication or deletion of the gene locus containing Nde1 and Ndel1." (PMID 35493069, 2022). "This was followed up through association analysis at the NDE1 locus, leading to the observation that a haplotype and its constituent SNPs associate with schizophrenia in this cohort, in a gender-dependent manner." (PMID 29142105, 2017). "In genetic association studies, NDE1 has been identified as a strong candidate for epilepsy and schizophrenia." (PMID 24785679, 2014). "Intriguingly, NDE1 CNV has been classified as a potential risk factor for a series of neuronal disorders including schizophrenia and epilepsy." (PMID 24785679, 2014). "Since this observation, NDE1 has been implicated in the etiology of schizophrenia in several studies world wide." (PMID 22363459, 2012). "One such peak was at chromosome 16p13 close to NDE1 which in a follow-up analysis revealed significant association to schizophrenia in Finnish families ascertained for schizophrenia." (PMID 22363459, 2012). "NDE1 was identified as a schizophrenia-associated locus following a genome wide linkage study of Finnish families conditioned on a common DISC1 risk variant." (PMID 19000741, 2009). "A recent study reported evidence for NDEL1 and NDE1 association with schizophrenia in an American population." (PMID 19000741, 2009). "Additionally, the first and fourth CpGs in the sum ranking were annotated to the C1D and NDE1 genes which have been respectively associated with Schizophrenia and epilepsy." (PMID 35105872, 2022). "Finally, in one study, high birth weight was associated with schizophrenia risk in subjects homozygous for risk alleles in a four-SNP haplotype spanning the NudE Neurodevelopment Protein 1 (NDE1) gene and one of its constituent SNPs (rs4781678)." (PMID 28822116, 2018). "Furthermore, NDE1 is independently implicated in major mental illness through its presence at 16p13.11, which is subject to duplications in schizophrenia, as well as being directly implicated through rare SNPs in patients." (PMID 29142105, 2017). "Although the mechanism for these effects remains unclear at this time, it is noteworthy that the original association between the NDE1 locus and schizophrenia in these families was significant only in females." (PMID 29142105, 2017). "Notably, a later study in the same sample of Finnish families also found sex-dependent evidence of association between a tag-haplotype in the NDE1 gene and risk of schizophrenia only in females." (PMID 23637818, 2013). "Furthermore, emerging evidence of genetic association (NDEL1, PCM1, PDE4B) and copy number variation (NDE1) implicate several DISC1-binding partners as risk factors for schizophrenia in their own right." (PMID 21195721, 2012). "The protein binding interaction between Nde1, Ndel1, and DISC1 is well-established and the genetic interaction between Nde1/Ndel1 and DISC1 is associated with an increased risk for schizophrenia." (PMID 35493069, 2022). "However, mutations in NDE1, which is one of the major LIS1-proteins interactors, result in a wide spectrum of brain diseases, including schizophrenia." (PMID 35309904, 2022). "Although the mechanism by which NDE1-DISC1 interactions could contribute to schizophrenia remains unclear, it is conceivable that NDE1 contributes to the morphological differentiation of oligodendrocytes by sequestering DISC1." (PMID 33390896, 2020).
schizophrenia (continued). "All three deletions included the region chr16:15387380–16198600 (and the genes MPV17L, c16orf45, KIAA0430, NDE1, MYH11, KIAA0866, c16orf63, ABCC1 and MRP6/AbCC6) indicating that a large deletion of this region may be a recurrent schizophrenia risk factor." (PMID 19197363, 2009). "That both NDE1 and NDEL1 express multiple isoforms in the brain, self-associate, complex with each other and bind to DISC1 provides a mechanism for fine-tuning the respective roles of these schizophrenia-related proteins in the cell." (PMID 19000741, 2009). "Similarly, both deletions and duplications at chromosomal locus 16p13.1, containing the NDE1 gene, are significantly over-represented in schizophrenia patients in Scottish and other European populations, with a similar deletion also seen in an African–American individual with the condition." (PMID 21195721, 2012). "Particularly, the interaction between disrupted in schizophrenia 1 (DISC1) and NDE1’s NUDE-C domain has been shown and has garnered attention, as it potentially relates NDE1 to schizophrenia." (PMID 33390896, 2020). "By conditioning genome-wide linkage data for schizophrenia on DISC1, a peak of linkage at chromosome 16p was observed, near to NDE1 (nuclear distribution element 1)." (PMID 29142105, 2017).